FREY1 (Frey regulator of sperm-oocyte fusion 1)
Description:
Key regulator for male fertility expressed transiently in round spermatids where it recruits IZUMO1 at the endoplasmic reticulum (ER) membrane and coordinates the oolemmal binding multimeric complex (IZUMO1 complex) assembly. Upon complete assembly of the IZUMO1 complex, its ER retention is released, facilitating IZUMO1 complex export to the acrosome. Through the interaction with SPPL2C, inhibits its intramembrane protease activity directly accessing the catalytic center of an I-CLiP.
Synonyms: C11orf94; FREY
Tractability: Antibody: UniProt predicts a signal peptide or a membrane-spanning region.
Gene: Protein-coding gene on chromosome 11 (45,906,513 to 45,907,272, reverse strand). Ensembl gene ENSG00000234776.
Subcellular location: Endoplasmic reticulum membrane
Gene Ontology:
Molecular function: protein-macromolecule adaptor activity
Biological process: fusion of sperm to egg plasma membrane involved in single fertilization; maintenance of protein localization in endoplasmic reticulum; sperm-egg recognition; protein-containing complex assembly
Cellular component: endoplasmic reticulum membrane; membrane
Genetic constraint (gnomAD): Loss-of-function variants: 9 observed, 9.81 expected, observed/expected ratio (o/e) 0.92, 90% interval 0.55 to 1.58. That is too few expected variants to judge how well the gene tolerates losing a copy. Missense variants: 158 observed, 117.09 expected, observed/expected ratio (o/e) 1.35, 90% interval 1.18 to 1.54. Synonymous variants: 81 observed, 54.84 expected, observed/expected ratio (o/e) 1.48, 90% interval 1.23 to 1.77.
Homologues: Orthologues: chimpanzee FREY1 (99% identical), dog FREY1 (87% identical), pig FREY1 (85% identical), mouse Frey1 (82% identical), rat Frey1 (82% identical), guinea pig FREY1 (60% identical).
Diseases named in the same sentence as FREY1 in open-access papers:
FREY1 is named in the same sentence as 5 diseases in open-access papers, as found by Europe PMC text mining. Sharing a sentence is not in itself a finding about the gene and the disease.
FREY1 shares sentences with these, for which no sentence is quoted: Infertility (3 papers); male infertility (2); genetic disorder (1); Intellectual disability (1); Potocki-Shaffer syndrome (1).